GHR (growth hormone receptor)
Diseases named in the same sentence as GHR in open-access papers (continued):
Sharing a sentence is not in itself a finding about the gene and the disease.
cancer (continued). "Moreover, a positive correlation was observed between GHR and markers of cancer stem cells, apoptosis inhibition, gemcitabine-deactivating CYP450s, increased angiogenesis and lymphangiogenesis, and senescence." (PMID 39000545, 2024). "We found 17 genes with hypomethylation or copy number gain and increased expression, including cancer-associated genes such as AGO1, GHR and FAT1, which might be potential oncogenes." (PMID 37245006, 2023). "Although gene transcription was not investigated in this study, CoAA is a potent nuclear receptor coactivator protein that is found to be overexpressed in a wide range of cancers, and may contribute to the proliferative actions of nuclear GHR." (PMID 37043098, 2023). "The STATs and their neighboring proteins are primarily associated with lymphocyte activation, cytokine-mediated signaling pathways, positive regulation of immune response, regulation of cytokine production, and growth hormone receptor signaling pathways in cancer." (PMID 36061181, 2022). "Here we aimed to determine whether a GHR antagonist (GHRA) could control cancer growth by sensitizing tumors to therapy through downregulation of ABC transporters in vivo." (PMID 35865483, 2022). "Tumor tissue from major cancer types as well as cells derived from them express both GH and GHR." (PMID 35966052, 2022). "Insight in their roles in GHR signaling can be applied for cancer and other therapeutic strategies." (PMID 33312162, 2020). "In such a scenario, proteasome inhibitors might be considered pro-cancer and pro-aging, as they prolong the residence time of the GHR at the cell surface." (PMID 33312162, 2020). "Organisms that lack GHR activity are virtually devoid of cancer." (PMID 33312162, 2020). "These are important open questions to understand the role of the GHR in cancer growth." (PMID 33312162, 2020). "Numerous studies entailing the GHR signaling pathway have been conducted for various cancers." (PMID 33312162, 2020). "Therefore, GHR inhibition appears to be a safer and validated point of intervention to suppress cancer growth and especially drug resistance, as well as in reducing circulating IGF-1 levels and improving insulin sensitivity." (PMID 33291663, 2020). "The scientific rationale for combining GHR-antagonism with existing anti-cancer treatments, that we present in this review, appear to be viable and systematic in vivo studies specifically validating this approach should pave the way for a clinical trial in immediate future." (PMID 32382711, 2019). "Therefore, targeting GHR action as well as identifying sexually dimorphic GH-regulated miRNAs can be a promising drug discovery exercise especially in relevant cancers." (PMID 32382711, 2019). "For example, miR-26b up-regulates the growth hormone levels by targeting lymphoid enhancer binding factor 1 (Lef-1) in GH3 cells, whereas miR-129-5p, miR-202 and two other miRNAs repress the human growth hormone receptor (GHR) expression levels in both normal and cancer cells." (PMID 28402262, 2017). "Consequently, GHR mRNA levels were significantly lower in malignant neoplasms compared to normal mammary tissue (p = 0.003)." (PMID 26370564, 2015). "Additionally, while high levels of GH and GHR expression are associated with poorer prognosis in several cancer types, this relationship is not consistent across all cancers—for example, it is not observed in liver cancer or renal clear cell carcinoma." (PMID 40806252, 2025). "Moreover, markers of cancer stem cells, ALDH1 and CXCR4, are strongly associated with GHR in PDAC." (PMID 39000545, 2024). "However, according to the concrete biological context, GHR may play the dual role of inhibiting and promoting cancer." (PMID 37854038, 2023). "Notably, GHR expression was suppressed in most cancers, with a few exceptions in the TCGA dataset." (PMID 35729324, 2022). "Our findings could also lead to testing GHR inhibition in other aggressive cancers." (PMID 36276070, 2022).
cancer (continued). "As genetic analysis of Ecuadorian subjects revealed mutation in the growth hormone receptor gene leading to severe growth hormone receptor (GHR) and IGF-I deficiencies, it was suggested that reduced expression of pro-growth specific genes protects against cancer and favors lifespan extension." (PMID 36513976, 2022). "Interestingly, miR-16 was reported to target GHR in different cancer cell lines." (PMID 34484116, 2021). "This raises the possibility that autocrine GHR activation might be a cancer-driver." (PMID 33312162, 2020). "Furthermore, patients with inherited GH signaling deficiency (Laron syndrome) do not develop cancer, and GH- or GHR-deficient animal models live longer and are resistant to age-related or chemically induced tumors." (PMID 31939481, 2019). "In stark contrast, GHR-deficient individuals show a lack of deaths from cancer." (PMID 29487568, 2018). "Pharmacologically, pegvisomant selectively blocks GHR, whereas compound D, another GHRA, inhibits both GHR and PRLR in cancer cells." (PMID 41515995, 2025). "A contrasting pattern of similarity emerges among carcinomas originating from uterine, pulmonary, and hepatic tissues, where genes like CTHRC1, ADH1B, GHR, DES, SFRP1, and RNF150 share similar weights." (PMID 39596491, 2024). "The GHA mouse, transgenic for a GHRA and with reduced IGF1, mimics a pharmacologic inhibition of GHR and provides an excellent model to assess the effects of multiple chemotherapeutic efficacies in presence of a GHRA for multiple cancer types." (PMID 35865483, 2022). "GHR inhibition decreased the activation of the AKT/mTOR and JAK/STAT pathways, which are major regulators of cancer cell proliferation and survival." (PMID 30617282, 2019). "A number of in vivo xenograft studies on bGH, GHRKO, as well as on mice transgenic for a GHR-antagonist (GHA mice) revealed an intrinsic resistance to tumor development and cancer progression due to abrogation of GHR function." (PMID 32382711, 2019). "Several studies indicate that in addition to its actions on GHR signalling, SOCS2 also has important actions in neuron development, the regulation of metabolism, mammary gland development and cancer as well as the immune response." (PMID 21980433, 2011). "In these types of cancers, GH plays a key role in creating a tumor microenvironment conducive to cancer progression, despite the fact that GHR is not overexpressed." (PMID 40806252, 2025). "In this regard, bGH transgenic mice, which develop spontaneous neoplasms at a higher rate than WT mice, also have markedly lower glycine levels than their WT counterparts, while the reverse is observed in GHR-knockout (GHRKO) mice, which are protected from cancer." (PMID 39000545, 2024). "CPEB3, GHR, GSTZ1, and KLF8 were especially crucial molecules in the onset and progression of diseases and have been widely investigated in HCC or other forms of malignant tumors." (PMID 36827016, 2023). "Yet, tumoral response to GHR antagonism coupled with any anti-cancer chemo- or targeted therapy in an in vivo setting had not been studied." (PMID 35865483, 2022). "Downstream in the GH/IGF1 signaling there is an strong analogy between inhibiting the GHR in mice with BM001 and the inhibitory effect of the small molecule S3I-201 on STAT3 with the same cancer cells: Both inhibitors resulted in tumor regression of MM231 xenografted mice." (PMID 35966052, 2022). "Although these patients have increased adiposity, no cancer has been found in an Ecuadorian cohort of patients with Laron syndrome, in contrast with cancer rates of >20% in heterozygous (GHR+/−) relatives and the control population." (PMID 35319491, 2022). "Mice with targeted global disruption of the GHR gene (GHRKO mice) are excellent models of LS, presenting an obese, growth-retarded phenotype with low levels of IGF-1 and insulin, high levels of GH, and enhanced resistance to diabetes and cancer." (PMID 33774052, 2021).
cancer (continued). "LPD3 cancer samples exhibited seven commonly overexpressed genes, including ERG, GHR and HDAC1." (PMID 32203215, 2020). "The GH-antagonist, pegvisomant, has been successfully used in cancer-derived cell lines, but does not inhibit autocrine-acting GH in cancer patients as it probably cannot interfere with intracellular GH/GHR signaling." (PMID 33312162, 2020). "Recent studies show physical and functional interactions of GHR with IGF-1R, which might strengthen its role in aging (and cancer)." (PMID 33312162, 2020). "GH was not induced in human colon adenocarcinoma tissue, but GHR was significantly upregulated in cancer cells compared to normal adjacent colon tissue." (PMID 31939481, 2019). "The growth hormone (GH) and growth hormone receptor (GHR) ligand–receptor pair are expressed in almost all types of human cancers and have been identified as a validated drug target by in vitro or in vivo studies in more than twelve cancer types." (PMID 31547367, 2019). "The absence of cancer in GHR‐deficient patients also suggests that cancer incidence may be fine‐tuned for each species: i.e. it is within a fairly narrow range described by longevity and body mass, even though the incidence of cancer can increase dramatically following single mutations." (PMID 29663630, 2018). "Malignant tumors with invasive growth of FFPE samples showed significantly lower gene expression of hormone receptors than tumors that were not invasive (ESR1 p = 0.014; PGR p = 0.033; PRLR p = 0.0006; GHR p = 0.011, respectively)." (PMID 27649560, 2016). "The 5p12 region harbors some important genes, for example GHR (growth hormone receptor), SEPPI, PAIP1, NNT and FGF10 that may be related to cancer (for complete list of genes in amplification regions)." (PMID 22363777, 2012). "Once activated, it is not surprising that the GHR may also play an important role in regulating cancer and chronic diseases." (PMID 39459020, 2024). "The ligand receptor pairs of GH/GH receptor (GHR) and IGF-I/IGF-I receptor (IGF-IR), although not proto-oncogenes or oncogenes themselves, frequently form an autocrine/paracrine loop implicated in multiple facets of cancer physiology." (PMID 35319491, 2022). "In cultured cancer cells, there is no direct link between GHR mRNA levels and growth rate." (PMID 35966052, 2022). "Since elevated activity of the GH/IGF-I pathway has been implicated in specific types of cancer, the low levels of IGF-I found in GHR−/− mice and LS patients, along with their insensitivity to GH, may be important for their relative lack of cancer." (PMID 28670222, 2017). "Furthermore, the data of this article also suggest that the dosage of rhGH may be a factor worth considering if rhGH is used to cancer patients without GHR expression." (PMID 30673747, 2019). "Importantly, studies in growth hormone receptor knock out mice (GHR-KO), discovered that miR-710 is at the core of a three-dimensional lncRNA–mRNA–miRNA regulatory network that defines phenotype in the GHR-KO animals, which is characterized by resistance to cancer and enhanced longevity." (PMID 31834924, 2019). "Therefore, one could hypothesize that global GHR disruption with its numerous beneficial effects, but not tissue-specific knockout of Ghr gene, may play a crucial role in lifespan extension and resistance to the development of cancer and diabetes seen in GHRKO dwarfs." (PMID 25855408, 2015).
tumor (80 papers, 2010 to 2026). "Growth hormone receptor (GHR), a member of the class I cytokine receptor superfamily, was down-regulation in the high-risk group and was related to chemoresistance, tumor metastasis, and poor prognosis." (PMID 35874741, 2022). "Our results showed that tumour weight was significantly smaller in mouse models with GHR deficiency than that in control group." (PMID 33492754, 2021). "In Ba/F3 murine lymphocyte cells, nuclear GHR localization was associated with oncogenic transformation and tumor metastasis due to enhanced nuclear translocation of phosphoSTAT5 generated at the cell surface by autocrine GH." (PMID 31939481, 2019). "In this study, there was an association between GHR expression and tumor stage and tumor differentiation." (PMID 23554765, 2012). "Subcellular GHR distribution may be an important determinant of tumor aggressiveness, since nuclear GHR expression is associated with high proliferative activity." (PMID 25580121, 2014). "In addition, xenograft mouse model experiment showed GHR deficiency inhibited tumour growth." (PMID 33492754, 2021). "Growth hormone receptor (GHR) signalling enhances migratory ability of tumour cells and excess IGF-1 production promotes angiogenesis." (PMID 41700740, 2026). "GHR expression in clinical tumor stage 3 was inversely correlated with survival in male patients alone and the combination of female and male patients (respectively, HR = 3.34, 3.40; p = 0.016, 0.0027)." (PMID 40806252, 2025). "The intricate crosstalk between GH action and the tumor microenvironment underscores the importance of exploring the relationship between GHR expression and patient survival in UC." (PMID 40806252, 2025). "Collectively, these findings highlight the potential of tumor-specific GHR expression as a prognostic indicator in NSCLC." (PMID 41515995, 2025). "Our analyses of the human PDAC tumor transcriptome showed that increasing GHR expression correlates positively with several gene expression modules, which collectively confer therapy resistance and immunosuppression in patients." (PMID 39000545, 2024). "Next, in xenograft tumors, we assess the RNA expression of EMT mediators that are positively correlated with GHR expression in human tumor samples." (PMID 39000545, 2024). "The most promising GHR-inhibiting compound, C#1, showed a 6-fold decrease in tumor growth in mice transplanted with the triple-negative mammary breast cancer cell line MDA-MM-231, at a dose of 1 mg/kg, three times weekly." (PMID 39459020, 2024). "As GH promotes lymphangiogenesis and the corresponding markers in PDAC correlate with GHR expression in our analyses, it can be expected that GHRAs can lower or inhibit tumor lymphangiogenesis to attenuate tumor growth, which remains to be tested in PDAC." (PMID 39000545, 2024). "In contrast, several researchers considered GHR a tumor promoter and a potential therapeutic target in HCC." (PMID 37854038, 2023). "In Cluster2, the up-regulated gene sets included growth receptors such as EGFR, TGFBR2, and GHR, as well as tumor suppressor genes found in apoptotic gene sets." (PMID 37226243, 2023). "Scholars from Texas MD Anderson Cancer observed that tumor cells exhibited slower growth and overcame sorafenib resistance by blocking GHR with pegvisomant in vitro." (PMID 37854038, 2023). "The mRNA expression levels of STMN1, CLSPN, MDK, RNFT2, PRR11, and RNF157 were significantly increased in HCC tumor tissue; on the contrary, GHR was significantly decreased compared with normal tissues." (PMID 37542549, 2023). "Overall, our data support a strong link between GHR and the regulation of cell migration and invasion in vitro, in vivo and in patient tumours." (PMID 35808822, 2022). "In our GBM cohort, GHR expression levels in bulk tumours and GH plasma levels were correlated, suggesting a possible contribution of circulating GH to tumour progression in these patients." (PMID 35808822, 2022).
tumor (continued). "GH acts directly on tumor vascular endothelial cells, while GHR is significantly expressed in the vascular endothelium, especially in neovascularization neocapillaries." (PMID 36016614, 2022). "Reducing the extracellular glucose concentration led to less tumor cell proliferation and less growth hormone receptor expression, measured on protein level by flow cytometry." (PMID 35574343, 2022). "As determined by immunohistochemistry analysis using an anti‐GHR antibody directed against the intracellular domain, GHR protein expression was detected in at least 30% of tumour area of GHRhigh cases." (PMID 35808822, 2022). "Several mouse models, as well as Pegvisomant treatment in Nude mouse xenografts, have confirmed that GHR antagonism is an effective monotherapy in slowing tumor growth." (PMID 35865483, 2022). "Reduced levels of IGF-1 lead to development of GH resistance, decreased expression of GHR due to hepatocellular damage by tumor cells, as well as, existence of feedback circuit at endocrine and paracrine loops." (PMID 36374927, 2022). "Treating mice with an antagonist to the isomiRs restored growth hormone receptor levels and suppressed tumor growth." (PMID 35729324, 2022). "Overall, it is likely that GHR overexpression sensitizes cells to GH stimulation, originating either from the tumour itself or from the circulation, potentially creating a vicious circle in which survival and expansion of GHR‐overexpressing cells are promoted." (PMID 35808822, 2022). "GHR expression is significantly higher in primary gastric adenocarcinoma compared with normal gastric mucosa and is in connection with tumour stage and tumour differentiation." (PMID 33492754, 2021). "The results showed that GHR was highly expressed in tumour tissues compared with in adjacent normal mucosa samples." (PMID 33492754, 2021). "Individuals with GHR deficiency (GHRD) caused by genetic mutations in the displayed GHR gene and congenital IGF1 appear to be protected against the development of neoplasms." (PMID 34178997, 2021). "GHR inhibition significantly reduced the tumor weight after 1 month compared with the vehicle control group." (PMID 32069380, 2020). "The tumor volume was also detected twice every week, and GHR silencing markedly decreased the tumor volume after 2 weeks." (PMID 32069380, 2020). "GHR is highly expressed in tumor samples compared with adjacent normal tissues, and it regulates tumor cell proliferation, apoptosis, tumor differentiation and tumor grade." (PMID 32970612, 2020). "The deficient GHR obviously inhibited cell proliferation in MDA‐MB‐231 and MCF‐7 cell lines, as well as tumor growth in xenograft mouse models established by MDA‐MB‐231 cells." (PMID 32069380, 2020). "To further verify the function of GHR on tumor growth, we generated stable cells in U2OS cells by transfecting lentivirus expressing shGHR (Knockdown) and shCtrl (Control) plasmid." (PMID 31725956, 2020). "Upregulation of selected components of these pathways has been observed in a wide range of malignant GH-responsive tumors, supporting the involvement of GH-induced GHR activation in tumor growth." (PMID 33291663, 2020). "In benign and malignant vascular tumors, including angiosarcoma, Kaposi’s sarcoma, hemangioendothelioma, and hemangioma, GHR is significantly upregulated in both cytoplasm and nuclei, implying that tumor cells are targets for GH action." (PMID 31939481, 2019). "DT treatment to GHR or ABCG2 knockdown xenografts significantly inhibited the tumor growth compared to control or DT alone treatment." (PMID 30617282, 2019). "The level of GHR expression on the tumor cell membrane surface has been considered to play a key role in tumor growth induced by rhGH." (PMID 30673747, 2019).